CCR2 (C-C motif chemokine receptor 2)
Diseases named in the same sentence as CCR2 in open-access papers (continued):
Sharing a sentence is not in itself a finding about the gene and the disease.
tumor (continued). "Therefore, our results suggested that adding SBRT improved the local tumor control of triple immunotherapy CCR2/5i + αPD-1 + GVAX, regardless of whether SBRT was administrated early or late in the immunotherapy treatment course." (PMID 35404390, 2022). "Similarly, STAT5 and p38MAPK could not be activated in CCR2−/− tumour tissues after tumour cell injection, indicating that CCL2‐induced tumour cell migration had a close relationship with JAK2‐STAT5 and p38MAPK pathway activation." (PMID 34464477, 2021). "Interestingly, while we observed a robust decrease in brain-infiltrating neutrophils in CCR2KO mice, we did not observe a decrease in liver- or tumor-infiltrating neutrophils, indicating that CCR2 is important for neutrophil recruitment specifically to the brain." (PMID 32391790, 2020). "Thus, in the absence of host CCR2, tumor cell-derived CCL2 that is induced downstream of cancer cell-expressed TRAIL-R fails to promote the presence of alternatively activated myeloid cells in the tumor microenvironment, coincident with diminished tumor growth." (PMID 28212753, 2017). "Interestingly, the indicated difference in CCL2 protein levels was also apparent in CCR2 KO mice, showing that it is not the mere extent of tumor burden that determines CCL2 amounts but, instead, the ability of tumor cells to produce CCL2, a capacity that is impaired in the absence of TRAIL-R." (PMID 28212753, 2017). "In addition, tumor growth in CCR2−/− mice was not significantly slowed by clodronate exposure." (PMID 25505466, 2014). "However, we cannot exclude the possibility that the secretion of a tumor-specific antigen may induce the expression of additional factors, which may induce the intrathymic negative selection in cooperation with CCR2-expressing Sirpα+ cDCs." (PMID 22815949, 2012). "Our trial did not assess tumor microenvironment components, but these potential compensatory changes support further exploration of combined CCL2/CCR2 and angiogenic inhibition." (PMID 38697618, 2024). "When we calculated the absolute numbers of myeloid subsets in the tumor, neutrophils, TAM and CCR2– monocytes were not significantly changed by BRAFi treatment." (PMID 38631706, 2024). "Blocking CCR2 with CCX872, a CCR2 antagonist, suppressed tumor growth without extending tumor-free survival and prolonged overall survival in neu+ mice." (PMID 37208442, 2023). "A linear regression analysis revealed that tumor levels of TNC and CCL2 each correlated with myeloid cell markers, including F4/80 (ADGRE1), CSFR1,and CX3CR1, but not with CCR2, with a higher correlation of TNC than CCL2 at the 3 week time point." (PMID 37176074, 2023). "We immunophenotyped tumours at 50 DPI and observed expansion of classical (CCR2+) and non-classical (CCR2−CX3CR1+) monocytes in dKO samples." (PMID 37605008, 2023). "There were no significant changes among these CCR2- and CX3CR1-expressing populations in the non-tumor peripheral tissues examined." (PMID 36685592, 2022). "Immunologic participation in complexes with trafficking chemokine receptors CCR2 and CXCR3 became significant in tumor but not plaque MF, which coincided with the observed influx of TILs observed with multispectral imaging." (PMID 34885092, 2021). "Given the prominent MDSC expression of CCR2, we assessed TC1 tumor growth in C57BL/6 mice lacking CCR2 (CCR2KO)." (PMID 33322474, 2020). "The majority of tumor-infiltrating mast cells expressed CXCR4 but not CCR2, CCR4, CCR5, CCR7, CXCR1, CXCR2 or CXCR7, while, mast cells in peritumoral or non-tumor tissues showed lower CXCR4 expression." (PMID 30808413, 2019). "Another approach to target the CCL-2/CCR-2 axis is to use siRNA, which targets CCL-2 expression in vivo by a complex of siRNAs with tumor penetrating peptides by non-covalent calcium cross-linking." (PMID 28660349, 2018).
tumor (continued). "We found that tumor-infiltrating CD4+CCR4+ T cells, but not CD4+CCR2+ T cells, were enriched in GBM tissues, suggesting that CD4+CCR4+ T cells had relatively specific infiltration in GBM." (PMID 29312296, 2017). "We observed a reduction of CCR2+Ly6Chi as a percentage of CD45+ cells, but not a reduction in cell number when IFNɣ was neutralized in IR-treated tumor." (PMID 29170400, 2017). "Peripheral blood was collected from RT-treated tumor-bearing (RT-TB) mice and non-RT-treated tumor-bearing (NT-TB) mice and the number of circulating IM (CD45+, CD11b+, Ly6C(high), Ly6G-, CCR2+) was determined by multicolor flow cytometry." (PMID 27852031, 2016). "Interestingly, whether upregulating or downregulating CCL2/CCR2, tumorigenesis was not be influenced in two independent cell-line pairs, arguing against the possibility that the observed increment or reduction in metastasis are the result of tumor growth rate." (PMID 26701209, 2016). "As CCR2-transduced CD8+ T cells do not differ in in vitro cytotoxic capacity from control-transduced cells, any beneficial effect on tumor growth was likely to be due to improved homing." (PMID 27177227, 2016). "Blocking of chemokine receptor CCR2 but not CCR1, CCR3, CCR5, CCR7 or CXCR3 on CTL007 with Abs significantly inhibited tumor cell apoptosis." (PMID 21450101, 2011). "Starting from the fact that an expanded expression of CCL2 was observed in tumor-assaulting macrophages, not in DLBCL cells, it was presumed that DE-DLBCL cells could produce CCL2 and influence CCR2-expressing macrophages." (PMID 40426926, 2025). "The CCR2 antagonist, combined with low-dose sorafenib, potentiated anti-liver tumor effects via upregulating intratumoral CD8+ T cells and enhanced the distribution of CD8+ T cells in the tumor milieu, without obvious toxicity." (PMID 38787372, 2024). "Modules 1–5 were rich in cytokines (e.g., IL6, IL10), cytokine receptors (e.g., CCR2, CCR4), and immune cell markers (e.g., CD3D, CD3E), indicating that the DEGs primarily regulate the immune microenvironment rather than tumor malignancy traits like proliferation and invasion." (PMID 38594692, 2024). "Interestingly, while we confirmed that these anti-tumor mechanisms do not depend on adaptive immune responses, we did observe a significant increase in CD8+ T-cells present within CCR2+ admixed tumors." (PMID 35140221, 2022). "Given the complete inhibition of innate immune cell trafficking into the pancreas and training of pancreatic myeloid cells following WGP treatment in CCR2−/− mice, we reasoned that CCR2−/− mice would also not show the beneficial anti-tumor immune effects of WGP training." (PMID 35140221, 2022). "Mint3 depletion attenuates chemotaxis toward CCL2 in macrophages/inflammatory monocytes due to the defect in ATP production via glycolysis without affecting the expression levels of CCR2 in macrophages, those of CCL2 in metastatic lungs, and serum in tumour-inoculated mice." (PMID 34621018, 2021). "Similarly, naphthofluorescein did not affect the expression levels of CCR2 in macrophages, those of CCL2 in metastatic lungs, and serum of tumour-inoculated mice." (PMID 34621018, 2021). "Since tumor intrinsic CCL2 may not be the only relevant source of CCL2, in our study we chose to target the CCL2 receptor, CCR2." (PMID 33247183, 2020). "We showed that mice lacking CCR2, or the use of a small-molecule inhibitor of CCR2, prevented MDSC recruitment to the tumors and derepressed host T cell responses, allowing immune activation and inhibition of tumor growth." (PMID 33322474, 2020). "However, tumor cells from neu+, neu+Ccl2-/-, and neu+Ccr2-/- mice grow at similar rates in culture, and adding neutralizing CCL2 antibodies to wild type tumor cells or exogenous CCL2 to Ccl2-/- tumor cells did not affect their proliferation." (PMID 27820834, 2016).
tumor (continued). "None of them showed CCL2 or CCR2 could promote NPC cell growth rate, tumor formation in contact-independent cell growth or anchorage-independent cell growth." (PMID 26701209, 2016). "Second, the TMA technique only displays a small piece of the original tumor tissue, the information contained may not be typical and the expression of CCL2 and CCR2 is evaluated subjectively." (PMID 27409666, 2016). "According to the results, the expression level of CCR2 in tumor tissues of female LUAD patients was not significantly different from that in normal tissues (p > 0.05), but female LUAD patients with high level of CCR2 exhibited a better overall survival (p = 0.001)." (PMID 34863300, 2021). "Indeed, we found CCR2 positive cells negative for IBA1 in human and murine tumor tissues." (PMID 32668709, 2020). "Neither CCR2 nor CCR5 could fulfil that role, indicating the likely requirement for transduction of multiple chemokine receptors into CAR-Ts intended to treat solid tumors, each with its own function along the path from circulation to tumor tissue." (PMID 31544847, 2019). "We analysed tumours for apoptosis (TUNEL+, 7.3 ± 0.9 vs. 6.5 ± 1.1%, mean ± S.E.M., N = 4) and proliferation (phospho-H3+, 3.1 ± 0.2 vs. 3.5 ± 0.2%) levels in Ccr2RFP/RFP vs. Ccr2+/+ mice at endpoint, but did not detect any significant difference between these groups." (PMID 31160587, 2019). "Because E9 cells are already transformed and do not require a progression phase for tumor growth and because alveolar macrophages differ in function and response from macrophages present near subcutaneous tumors, we tested whether CCL2/CCR2 signaling was required for de novo lung tumor formation." (PMID 25505466, 2014).
cancer (411 papers, 2010 to 2026). A tumor composed of atypical neoplastic, often pleomorphic cells that invade other tissues. "Pharmacological inhibition of CCR2 with RS504393 attenuates both cancer-associated adipocyte formation and cisplatin resistance, highlighting the therapeutic potential of targeting the CCL2-CCR2 axis in HNSCC." (PMID 41276817, 2025). "In CRC samples, higher levels of myeloid cell CCR2 were seen in tumors harboring mismatch repair deficiency/microsatellite instability–high than in microsatellite stable carcinomas, and this difference was predominant when measuring CCR2 in CD68+ TAMs." (PMID 39918395, 2025). "In this regard, CCR2 has been linked to a variety of immuno-inflammatory diseases, including cancer." (PMID 39201670, 2024). "A recently discovered chemokine PSMP—PC3-secreted microprotein (microseminoprotein, prostate-associated MSMP), which is over-expressed in cancer and promotes hepatic fibrosis, has an affinity for CCR2 on a level similar to the most potent CCL2." (PMID 37834457, 2023). "Both CXCR2 and CCR2 have been associated with chemoresistance in multiple cancer types, including HGSOC." (PMID 37509311, 2023). "TAM recruitment is highly linked to the CCL2/CCR2 axis, and in many cancer models, blocking this axis has led to a significant decrease in TAM populations." (PMID 34209703, 2021). "And the CCL2/CCR2 axis has generated increasing interest in recent years due to its association with the progression of cancer." (PMID 34187403, 2021). "In various cancers, the activation of the CCL2/CCR2 axis, that mediates the crosstalk between TAMs and tumor cells, was associated with metastases and cancer progression." (PMID 34830817, 2021). "The chemokine ligand CCL2 and its receptor CCR2 are implicated in the initiation and progression of various cancers." (PMID 34464477, 2021). "The association between low and high expression of CCL2 or CCR2 and cancer prognosis has been studied for several human diseases." (PMID 34944943, 2021). "Most of them show a clear link between high CCL2 expression and bad cancer prognosis, or low CCL2 expression and good prognosis, or polymorphism of CCR2 and prognosis of cancer diseases." (PMID 34944943, 2021). "CCL2 and CCR2 can function as diagnostic biomarkers, and are correlated with the prognosis and poor overall survival in cancer patients." (PMID 34464477, 2021). "The CCL2/CCR2 recruitment mechanism is implicated in a number of cancers and a CCR2 inhibitor to be administered alongside chemotherapy is currently in phase 1b trials." (PMID 32038499, 2020). "The upregulation of CCR2 has been found to be associated with advanced cancer, metastasis, and relapse." (PMID 32471499, 2020). "In particular, CCL2/CCR2 over-expression promoted the proliferation of HCC cells in response to apigenin or co-culture with cancer-associated fibroblasts." (PMID 31377844, 2019). "The 3’-UTR of CCR2 has also been linked to metastatic suppression in some cancers." (PMID 40909274, 2025). "Upregulation of CCL2/CCR2 is linked to cancer progression, metastasis, and relapse." (PMID 39192980, 2024). "In a phase II clinical trial for patients with cancer metastatic to the bone, an anti-CCR2 antibody (MLN1202) caused considerable reduction in urinary N-telopeptide (uNTX) values after 43 days of treatment in for 14 out of 43 patients with bone metastasis (ClinicalTrials.gov ID: NCT01015560)." (PMID 33603130, 2022). "High CCR2 expression is associated with a poor prognosis of various cancers, while inhibition of CCR2 expression may enhance the inhibitory effect of PD-1 on tumors." (PMID 36186485, 2022). "Therefore, CCL2 and CCR2 enable us to explore the sophisticated mechanisms underlying cancer development and provide potential options for treating malignant tumours." (PMID 34464477, 2021).
cancer (continued). "Consequently, CCL2 and CCR2 enable us to explore the sophisticated mechanisms underlying cancer development and provide potential options for treating malignant tumours." (PMID 34464477, 2021). "Notably, the CCR2-V64I polymorphism, found in DNA isolated from the PB of patients with various cancers, was associated with the increased risk of cancer development." (PMID 29751565, 2018). "Thus, it is not surprising to observe that an elevated expression of CCL2/CCR2 is present in several cancer types and is associated with adverse clinical outcomes." (PMID 27409666, 2016). "Therefore, MMP-9, as one of the mediators of the CCL2/CCR2 axis interaction, may cause the inhibition of cancer cell migration and invasion." (PMID 28424406, 2017). "Thus the CCR2-64I variant might be associated with reduced risk of developing cancer in the early phase." (PMID 20537184, 2010). "Our results demonstrate that cancer‐derived CCL2 acts as a signaling molecule that regulates lipid metabolism in adipose tissues through the CCL2/CCR2/PPARα pathway." (PMID 41160815, 2026). "C‐C motif chemokine ligand 2 (CCL2) is a nerve‐secreted chemokine that mediates the neural invasion of CCR2‐positive cancer cells." (PMID 41556039, 2026). "This evidence strongly indicates that the FA‐HIF‐1α‐CCL2 axis in cancer plays a pivotal role in activating CCR2‐mediated signaling within the adjacent adipose tissue under obese condition." (PMID 41160815, 2026). "In fact, some scholars have also provided some insights into the potential therapeutic benefits of using novel delivery systems targeting the CCL2/CCR2 axis to treat cancer and inflammation." (PMID 41445742, 2025). "Cancer cells also exhibited increased chemokine receptor 2 (CCR2) expression in primary sensory neurons." (PMID 41008336, 2025). "CCL2, binding to its receptor C–C chemokine receptor type 2 (CCR2), acts as a chemokine, attracting monocytes during cancer progression." (PMID 39749673, 2025). "Therapeutics that specifically target the CCL2/CCR2 chemokine axis are currently in clinical trials for cancer indications." (PMID 39883518, 2025). "CCR2, through its interaction with CCL2, has been associated with disease outcomes in multiple cancer types, such as hepatic, prostatic, mammary, and colorectal malignancies." (PMID 40909274, 2025). "CCR2 also plays a role in cancer metastasis, with CCR2 KO’d cells metastasizing significantly less frequently." (PMID 40909274, 2025). "PDGF, CD154 and/or CCL2.73–75 Conversely, fibroblasts and macrophages are important sources of CCL2 and HGF,76,77 which act on cancer cells to increase CCR2 and MET signaling during DCIS progression." (PMID 40736024, 2025). "The axis CCL2 and its receptor CCR2 has been established as an early marker of diagnosis and prognosis in different types of cancers." (PMID 39305371, 2025). "In particular, this study shows that SCs-derived CCL7 binds to its receptor CCR2 in cancer cells to upregulate the expression of the EMT-related factor TIMP1, while TIMP1 binds to CD63 to enhance the expression of CCL7 in SCs." (PMID 40037534, 2025). "M2 polarization, enhanced by the CCL2/CCR2 axis, correlates with cancer aggressiveness in DE-DLBCL, presenting a potential therapeutic target." (PMID 40426926, 2025). "For example, CCL8 derived from cancer cells binds to its receptor, C–C chemokine receptor 2 (CCR2) on macrophages, attracting macrophages." (PMID 38976211, 2025). "In summary, CCR2-KO combined with Merestinib treatment results in the most significant reduction in growth of breast xenografts and is characterized by reduced carcinoma cell proliferation and survival." (PMID 40736024, 2025). "We also show prominent expression of CCR2 protein in intratumor myeloid cells from the vast majority of human carcinomas from different locations including lung, colorectal, and pancreatic malignancies." (PMID 39918395, 2025).